DLG2 (discs large MAGUK scaffold protein 2)
Description:
Required for perception of chronic pain through NMDA receptor signaling. Regulates surface expression of NMDA receptors in dorsal horn neurons of the spinal cord. Interacts with the cytoplasmic tail of NMDA receptor subunits as well as inward rectifying potassium channels. Involved in regulation of synaptic stability at cholinergic synapses. Part of the postsynaptic protein scaffold of excitatory synapses (By similarity).
Synonyms: Chapsyn-110; PSD-93; PSD93; PPP1R58
Tractability: Antibody: its Gene Ontology location is reachable by antibodies, with high confidence; UniProt places it where antibodies can reach, with medium confidence; the Human Protein Atlas places it where antibodies can reach. PROTAC: ubiquitination databases record sites on it; its protein half-life has been measured.
Gene: Protein-coding gene on chromosome 11 (83,455,012 to 85,628,335, reverse strand). Ensembl gene ENSG00000150672.
Subcellular location: Cell membrane; Postsynaptic density; Synapse; Membrane; Cell projection, axon; Perikaryon
Subcellular location (Human Protein Atlas): Plasma membrane; Vesicles
Pathways (Reactome):
Neuronal System: Assembly and cell surface presentation of NMDA receptors; Long-term potentiation; Negative regulation of NMDA receptor-mediated neuronal transmission; Neurexins and neuroligins; Ras activation upon Ca2+ influx through NMDA receptor; Unblocking of NMDA receptors, glutamate binding and activation
Signal Transduction: RAF/MAP kinase cascade
Gene Ontology:
Molecular function: kinase binding; protein binding; GMP kinase activity; ionotropic glutamate receptor binding; protein kinase binding; structural constituent of postsynaptic density
Biological process: anterograde axonal protein transport; cell-cell adhesion; cellular response to potassium ion; chemical synaptic transmission; establishment or maintenance of epithelial cell apical/basal polarity; nervous system development; protein localization to synapse; receptor clustering; receptor localization to synapse; regulation of postsynaptic membrane neurotransmitter receptor levels; retrograde axonal protein transport; clustering of voltage-gated potassium channels; GDP metabolic process; GMP metabolic process; maintenance of postsynaptic density structure; neurotransmitter receptor localization to postsynaptic specialization membrane
Cellular component: adherens junction; basolateral plasma membrane; cytosol; juxtaparanode region of axon; membrane; neuromuscular junction; neuron projection; perikaryon; plasma membrane; postsynaptic density; postsynaptic density membrane; voltage-gated potassium channel complex; axon; axon cytoplasm; axon initial segment; cell junction; glutamatergic synapse; postsynaptic membrane; synapse; synaptic vesicle membrane
Genetic constraint (gnomAD): Loss-of-function variants: 31 observed, 94.28 expected, observed/expected ratio (o/e) 0.33, 90% interval 0.25 to 0.44. The upper end of that interval is the gene's LOEUF score, 0.44, which puts it in group 1 of 6, group 1 being the genes least tolerant of losing a copy. Missense variants: 851 observed, 1,014 expected, observed/expected ratio (o/e) 0.84, 90% interval 0.79 to 0.89. Synonymous variants: 366 observed, 367.86 expected, observed/expected ratio (o/e) 0.99, 90% interval 0.91 to 1.09.
Homologues: Orthologues: chimpanzee DLG2 (99% identical), macaque DLG2 (99% identical), dog DLG2 (98% identical), pig DLG2 (98% identical), rabbit DLG2 (97% identical), rat Dlg2 (94% identical), mouse Dlg2 (94% identical), guinea pig DLG2 (87% identical), tropical clawed frog dlg2 (80% identical), zebrafish dlg2 (73% identical). Paralogues in human: DLG1 (66% identical), DLG3 (55% identical), DLG4 (53% identical).
Diseases named in the same sentence as DLG2 in open-access papers:
DLG2 is named in the same sentence as 92 diseases in open-access papers, as found by Europe PMC text mining. Sharing a sentence is not in itself a finding about the gene and the disease. The quoted sentences say what the papers report.
schizophrenia (31 papers, 2011 to 2024). A major psychotic disorder characterized by abnormalities in the perception or expression of reality. "Variations in the Dlg2 gene have been linked to increased risk for psychiatric disorders, including schizophrenia, autism spectrum disorders, intellectual disability, bipolar disorder, attention deficit hyperactivity disorder, and pubertal disorders." (PMID 37705179, 2023). "To date, neither gene is known to be causative of any disease; however, DLG1 has been associated with cleft-lip/palate and depression, and DLG2 has been associated with schizophrenia and renal oncocytoma." (PMID 37422595, 2023). "The Dlg2 gene encodes the synaptic protein PSD3, and Dlg2 disruption has been associated with psychiatric disorders, including schizophrenia." (PMID 38123893, 2023). "Genetic studies implicate disruption to the DLG2 gene in copy number variants as increasing risk for schizophrenia, autism spectrum disorders and intellectual disability." (PMID 35075790, 2022). "Copy number variants indicating loss of function in the DLG2 gene have been associated with markedly increased risk for schizophrenia, autism spectrum disorder, and intellectual disability." (PMID 35115661, 2022). "Mutations affecting DLG2 are emerging as a genetic risk factor associated with neurodevelopmental psychiatric disorders including schizophrenia, autism spectrum disorder, and bipolar disorder." (PMID 35118804, 2022). "Studies using a large-scale genetic analysis of human patients have indicated that the disruption of the Dlg2 gene is closely associated with psychiatric disorders, including schizophrenia, intellectual disability, and autism spectrum disorder (ASD) in humans." (PMID 35966008, 2022). "Mutations affecting DLG2, the gene encoding PSD93, have been associated with a series of neurodevelopmental psychiatric disorders, including schizophrenia and potentially BD." (PMID 36115840, 2022). "Haploinsufficiency of Dlg2 is a risk for common developmental neuropsychiatric disorders including autism spectrum disorder and schizophrenia." (PMID 35118804, 2022). "Genetic variations at the DLG2 gene locus are linked to multiple psychiatric disorders including schizophrenia, bipolar, autism spectrum, attention deficit hyperactivity, intellectual disability, and Parkinson’s disease." (PMID 35115661, 2022). "Genetic variations resulting in the loss of function of the discs large homologs (DLG2)/postsynaptic density protein-93 (PSD-93) gene have been implicated in the increased risk for schizophrenia, intellectual disability, and autism spectrum disorders (ASDs)." (PMID 35966008, 2022). "It has been established that genetic variations in DLG2 are associated with neurodevelopmental disorders, including schizophrenia and intellectual disability." (PMID 32164788, 2020). "For example, de novo loss-of-function mutations in DLG2 have been repeatedly found in schizophrenia patients." (PMID 32164788, 2020). "In the present study, we present results indicating that genetic disruption of Dlg2, which has been mainly regarded as a schizophrenia-susceptibility gene, leads to abnormalities in ASD-relevant behavioral realms, such as sociability and repetitive behavior." (PMID 32164788, 2020). "In patients with schizophrenia, genetic variants of DLG2 are linked to aberrant structural features of the putamen." (PMID 32164788, 2020). "Disruption of multiple genes, including DLG2, owing to rare copy number variations (CNVs) is associated with schizophrenia." (PMID 32164788, 2020). "Allelic variants and somatic mosaicism of Dlg2 are associated with schizophrenia and other neurodevelopmental disorders." (PMID 30586380, 2018). "Using this system we focused on three postsynaptic proteins DISC1, TNIK and PSD-93/DLG2 each of which is encoded by a schizophrenia susceptibility gene." (PMID 21440632, 2011).
schizophrenia (continued). "The study suggests that Dlg2 gene disruption, which has been linked to neuropsychiatric disorders, including schizophrenia, may cause relatively specific impairments in reversal learning, an important aspect of cognitive flexibility." (PMID 38123893, 2023). "Impairments in cognitive flexibility have been demonstrated in patient populations, including those suffering from schizophrenia, autism spectrum disorder, and attention deficit hyperactivity disorder, for which genetic variations in the Dlg2 gene are a risk factor for." (PMID 37705179, 2023). "DLG2 has previously been associated with schizophrenia and autism." (PMID 35246634, 2022). "Previous studies have highlighted a close association between mutations in Dlg2 and schizophrenia." (PMID 32164788, 2020). "In addition, genetic variants of DLG2 are known to be associated with altered volumes of the putamen in schizophrenia patients." (PMID 32164788, 2020). "Although DLG2 is well known as a schizophrenia-susceptibility gene, the mechanisms that link DLG2 gene disruption with ASD-like behaviors remain unclear." (PMID 32164788, 2020). "DLG2 has been associated with Parkinson’s disease, schizophrenia, and other neurological disorders." (PMID 30442960, 2018). "The study suggests that Dlg2 gene disruption may cause relatively specific impairments in reversal learning, which is an important aspect of cognitive flexibility and disrupted in neuropsychiatric disorders, including schizophrenia." (PMID 38123893, 2023). "Few studies had linked DLG4 variants to schizophrenia and NDDs such as ID and ASD; DLG2 variants to ASD, schizophrenia, and bipolar disorder; and truncating DLG3 variants to X-linked ID." (PMID 35457207, 2022). "Genetic variations in DLG2/PSD-93 have been implicated in various disorders, including schizophrenia, intellectual disability, and ASD, as well as neurodegenerative disorders, such as AD and Parkinson’s disease (PD)." (PMID 35966008, 2022). "The DLG family members, DLG1 and DLG2, which also interact with DLGAPs and NMDA receptors have been linked to schizophrenia as well." (PMID 28870203, 2017). "As regards rare CNVs in our own schizophrenia case–control sample, we found two partial deletions of the DLG2 locus (one case and one control) and one case duplication affecting the ROBO1 locus; all three CNVs were exon-disrupting." (PMID 26460480, 2015). "Dlg2 (PSD-93/Chapsyn-110) is a scaffolding protein of the post-synaptic density deleted in schizophrenia in a study of Genome-Wide Copy Number Variation and shows a reduction in protein expression in post-mortem brain samples from schizophrenics." (PMID 21440632, 2011). "While there is no clear predilection for these changes in retinal structure and function in particular regions of the retina of patients diagnosed with schizophrenia, it is possible that DLG2, while expressed exclusively in the fovea, contributes to these retinal changes." (PMID 39337590, 2024). "Cognitive impairment in the form of deficits in reversal learning seen in the Dlg2+/− rat model here may resemble some of the cognitive impairments observed in patients with schizophrenia and in patients with psychosis." (PMID 37705179, 2023). "The gene DLG2, which encodes a scaffold protein belonging to the membrane-associated guanylate kinase (MAGUK) family and is active at postsynaptic sites, is associated with neurodevelopmental disorders, schizophrenia and cognition in humans." (PMID 29609558, 2018). "Moreover, the expression level of DLG1 and DLG2 was also found to be significantly skewed in a schizophrenia rat model and in schizophrenic patients." (PMID 28870203, 2017). "Moreover, mouse knockouts of Dlg2 show hypofunction of NMDA receptor signaling, a process implicated in schizophrenia." (PMID 21440632, 2011). "DLG2 is the only one among these genes to be directly involved in NMDA receptor signaling and it makes an obvious candidate for involvement in schizophrenia pathophysiology." (PMID 26460480, 2015).
schizophrenia (continued). "Particularly interesting are SF3B1, DLG2 and FOXP1 because of the strong association for the SF3B1 in the PGC meta-analysis and the previous evidence implicating DLG2 and FOXP1 in schizophrenia and other neurodevelopmental disorders." (PMID 26460480, 2015). "The translational power of this is demonstrated by the finding that Dlg2 knockout mice and humans with DLG2 CNV deletions, reported in schizophrenia patients, show strikingly similar impairments in cognitive function determined by an identical object-located paired associates task." (PMID 35393394, 2022). "The link of DLG1, DLG2 and DLG4 to schizophrenia has been well documented." (PMID 28870203, 2017).
neuroblastoma (12 papers, 2020 to 2025). Neuroblastoma (NB) is the most common solid, extracranial childhood tumor. "In neuroblastoma, the protein encoded by DLG2‐isoform 7 positively regulates and increases the expression of LIN7A by binding to LIN7A, which significantly reduces the proliferative viability of neuroblastoma cells and increases apoptosis of tumour cells." (PMID 40801824, 2025). "A study on high-risk neuroblastomas having a genetic disruption of the Dlg2 gene has shown that DLG2/PSD-93 expression drives differentiation of neuroblastoma cells via increases in the TrkA expression." (PMID 35966008, 2022). "Higher expression of DLG2 was related to the survival of neuroblastoma patients, and it was negatively associated with MYCN status and tumor stage." (PMID 35111846, 2022). "DLG2 knockdown led to forced cell cycle progression and predicted a poor prognosis of neuroblastoma patients." (PMID 39856747, 2025). "Due to its location on chromosome 11q, which is deleted in aggressive neuroblastomas, DLG2 has been considered a candidate neuroblastoma tumour suppressor gene." (PMID 38398114, 2024). "Recently, low DLG2 expression in osteosarcoma, ovarian cancer and neuroblastoma has been identified as contributing to disease etiology, with low DLG2 expression in neuroblastoma showing increased cell proliferation and poor survival." (PMID 35499706, 2022). "DLG2 expression is shown to inhibit tumour growth in vivo and drive neuroblastoma cell differentiation." (PMID 34769149, 2021). "Whilst DLG1 showed a decrease in both isoforms with increased INSS stage, only the full length L27 containing DLG2 transcripts DLG2-isoform 7/8 showed a decrease in expression in high stage neuroblastoma." (PMID 33726762, 2021). "Previous studies have described DLG2 expression in the “bridge cell” signature between Schwann cell precursors (SCP) and Schwann cells, and late bridge cell signatures in neuroblastoma tumours have been linked to better prognosis." (PMID 34769149, 2021). "It has been recently reported that DLG2 plays an important role in the nerve growth factor (NGF)-induced differentiation through the regulation of its receptor TrkA expression via positive feedback interactions between TrkA and DLG2 in human neuroblastoma cells." (PMID 35966008, 2022). "Recently, low DLG2 expression has been found in osteosarcoma, ovarian cancer and neuroblastoma." (PMID 35499706, 2022). "We evaluated the DLG gene family and the LIN7 gene family for their expression in differently INSS staged neuroblastoma from publically available data and primary tumors, we included two distinct DLG1 and DLG2 N-terminal transcript isoforms encoding L27 domains for their expression." (PMID 33726762, 2021). "In neuroblastoma only two DLG2 isoforms were expressed: isoform 2 and isoform 7/8." (PMID 33726762, 2021). "Interestingly, both SHANK2 and DLG2 are post-synaptic anchor proteins that are both able to modulate transcriptional outcome in neuroblastoma cells from proliferation cues to differentiation cues." (PMID 34885007, 2021). "We could show that the protein encoded by DLG2-isoform 7 could bind to LIN7A, and increased DLG2-isoform 7 gene expression increased the expression of LIN7A, this reduced neuroblastoma cell proliferation and viability, with increased BAX/BCL2 ratio indicating increased apoptosis." (PMID 33726762, 2021). "Gene expression of DLG2 was found to be significantly lower in 11q-deleted NB tumor data when MYCN amplification was excluded, in two independent neuroblastoma primary datasets (3 and 4)." (PMID 32312269, 2020). "DLG2 expression is negatively correlated with MYCN amplification and its location on chromosome 11q, a common chromosomal deletion in unfavourable neuroblastomas, further validates that it is a potential neuroblastoma prognostic biomarker." (PMID 38398114, 2024).
neuroblastoma (continued). "This was given emphasis when Siaw and colleagues proposed that ALK activation in neuroblastoma can inhibit DLG2 transcription via ERK1/2 and specificity protein 1 (SP1) signalling, thus impairing DLG2-induced differentiation." (PMID 34769149, 2021). "Functionality of DLG2 isoforms and of LIN7A were evaluated in the 11q-deleted neuroblastoma cell line SKNAS." (PMID 33726762, 2021).
autism spectrum disorder (10 papers, 2020 to 2024). A spectrum of developmental disorders that includes autism, and Asperger syndrome. "More recently, variants and knockout studies of DLG2 have been linked in to delayed puberty and autism spectrum disorders." (PMID 37422595, 2023). "A recent study has demonstrated that mutations in the DLG2 promoter region are significantly associated with autism spectrum disorder (ASD)." (PMID 32164788, 2020). "Interestingly, we also observed that 28 genes actively expressed at this stage, including genes such as NFIA, CDH13, TCF4, and DLG2, were associated with intellectual disabilities, autism spectrum disorders, irritability, and depression." (PMID 39452151, 2024). "Specifically, DLG2 encodes an excitatory postsynaptic protein involved in the development of striatal connectivity; this gene has been related to autism spectrum disorders in humans, and mice with a deficiency in DLG2 activity showed decreased sociability and increased stereotypies." (PMID 36669004, 2022). "On the other hand, the involvement of DLG2 in autism spectrum disorder (ASD) has not been extensively studied." (PMID 32164788, 2020).
autism (9 papers, 2011 to 2024). Persistent deficits in social interaction and communication and interaction as well as a markedly restricted repertoire of activity and interest as well as repetitive patterns of behavior. "As possible targets we chose long genes which are associated with autism, namely Nrxn1, Nlgn1, contactin-associated protein 2 (Cntnap2) and discs large MAGUK scaffold protein 2 (Dlg2)." (PMID 36768419, 2023). "DLG2 mutant mice display deficits in some forms of associative learning, and autism-like behaviors, including decreased sociability and increased repetitive self-grooming." (PMID 35205368, 2022). "Nevertheless, the mechanisms that link DLG2-associated mutations to autism-relevant behavioral abnormalities have remained elusive." (PMID 32164788, 2020). "Here, we present results indicating that a DLG2 deficiency induces autism-related behavioral phenotypes, including aberrant locomotor responses to novelty, decreased social approach, and significantly increased repetitive behavior." (PMID 32164788, 2020). "DLG2 deficiency induces autism-related behavioral phenotypes." (PMID 39654053, 2024). "In the past, a hypothetical link was proposed between autism genes and DLG2 through a PI3K synaptic pathway." (PMID 28724449, 2017).